FOSL1 (FOS like 1, AP-1 transcription factor subunit)
Diseases named in the same sentence as FOSL1 in open-access papers (continued):
Sharing a sentence is not in itself a finding about the gene and the disease.
malaria (1 paper, 2017). Malaria is a serious and sometimes fatal disease caused by a parasite that commonly infects a certain type of mosquito which feeds on humans. "Enhanced IFN-I response in chimeric FOSL1 knockout (KO) mice after malaria parasite or vesicular stomatitis virus (VSV) infection." (PMID 28049150, 2017). "These in vivo studies provide further evidence that FOSL1 plays a critical role in the regulation of the innate immune response to malaria parasite and viral infection and reveal a previously uncharacterized function of FOSL1 in inhibiting IFN-I signaling." (PMID 28049150, 2017). "To investigate the functional importance of FOSL1 in regulating innate immune responses in malaria, we first generated chimeric FOSL1 KO mice by reconstituting irradiated recipient mice with Fosl1 KO bone marrow cells using CRISPR/Cas9." (PMID 28049150, 2017). "To dissect the complex host-parasite interactions and the molecular mechanisms underlying innate immune responses to infections, here we investigate the role of FOS-like antigen 1 (FOSL1) in regulating the host type I interferon (IFN-I) response to malaria parasite and viral infections." (PMID 28049150, 2017). "In this report, we show that, after stimulation with poly(I:C) or malaria parasite-infected red blood cells (iRBCs), FOSL1 was “translocated” from the nucleus to the cytoplasm, where it interacted with TRAF3 and TRIF to reduce IRF3 phosphorylation and IFN-I signaling." (PMID 28049150, 2017). "Screening compound libraries for small molecules to block FOSL1 expression in cytoplasm or its interaction with TRAF3/TRIF/TBK1 may lead to therapies that can improve IFN-I response in malaria and other diseases." (PMID 28049150, 2017). "FOSL1 KO chimeric mice had significantly increased IFN-α and IFN-β production in the blood and spleen at day 1 and day 4 after malaria parasite infection, and IFN-I has been associated with inhibition of the growth of blood and liver stages of malaria parasites." (PMID 28049150, 2017). "In this study, we investigated the role of FOSL1, a molecule previously known as a transcription factor, in negatively regulating IFN-I responses to malaria and viral infections." (PMID 28049150, 2017). "Thus, our findings have identified a new role for FOSL1 in negatively regulating the host IFN-I response to malaria and viral infections and have identified a potential drug target for controlling malaria and other diseases." (PMID 28049150, 2017). "Indeed, FOSL1 KO chimeric mice had lower parasitemia or VSV titers and longer survival times after malaria parasite or virus infections." (PMID 28049150, 2017). "Our results suggest that FOSL1 plays a negative role in IFN-I production and malaria protection." (PMID 28049150, 2017).
malignant pleural mesothelioma (1 paper, 2019). A malignant neoplasm that arises from mesothelial cells in the pleura and shows a diffuse growth pattern. "An additive or synergistic effect of JQ1 in combination with cisplatin has been observed also in malignant pleural mesothelioma cell lines, associated with downregulation of c-MYC and FRA-1 (FOSL1)." (PMID 30841549, 2019).
Osteoblastoma (1 paper, 2023). A rare benign bone-forming neoplasm usually arising from the spine. "We next delved into the three FOSL1 wild‐type and immunonegative cases of desmoplastic fibroblastoma and found that two of these contained breakpoints in the final exon of FOS, identical to the recurrent alterations that typify osteoblastoma." (PMID 36426824, 2023).
osteosclerosis (1 paper, 2022). Abnormally high bone density. "In contrast to Fosl1 knockout mice, Fosl1 transgenic mice (H2-Fosl1-LTR) develop osteosclerosis, a bone disorder, which causes a progressive increase in bone mass of the entire skeleton." (PMID 35163444, 2022).
periodontitis (1 paper, 2025). An acute or chronic inflammatory process that affects the tissues that surround and support the teeth. "Additional genes encoding FOS and JUN family members (JUNB, FOSB, FOSL1) were significantly downregulated in periodontitis." (PMID 41124422, 2025).
peripheral nerve injury (1 paper, 2023). Injury to a peripheral nerve. "In addition to the positive regulation of FOSL1 on EPHB2, the dynamic changes of FOSL1 and EPHB2 following peripheral nerve injury were also comparable." (PMID 37949219, 2023).
polycystic kidney disease (1 paper, 2025). A usually autosomal dominant and less frequently autosomal recessive genetic disorder characterized by the presence of numerous cysts in the kidneys leading to end-stage renal failure. "While abnormal expression of FOSL1 gene has been implicated in renal pathologies such as renal cell carcinoma and AKI, there is no report on the association between FOSL1 and polycystic kidney diseases so far." (PMID 40570958, 2025).
pterygium (1 paper, 2021). A wedge-shaped fibrovascular lesion arising from the bulbar conjunctiva and extending to the cornea. "We added 4 of the top upregulated genes in pterygium: CLEC18A, FOSL1, PPMN1 and SPRR3." (PMID 34769520, 2021).
seminoma (1 paper, 2023). A radiosensitive malignant germ cell tumor found in the testis (especially undescended), and extragonadal sites (anterior mediastinum and pineal gland). "Altogether, these results revealed the key role of TFAP2C in promoting migration and invasion by directly regulating genes such as FOSL1, LYPD3 and ITGA6 in the seminoma cell line, promoting further study to understand its role in seminoma tumorigenesis." (PMID 38123589, 2023).
trisomy 16 (1 paper, 2022). "Among the DMGs in miscarriages with trisomy 16, two genes (FOSL1 and PCDH12) were involved in placental development (GO:0001890)." (PMID 35064135, 2022).
vascular tumours (1 paper, 2023). "Rearrangements in FOSL1 and FOS were identified in 10/15 and 2/15 desmoplastic fibroblastomas respectively, which mirrors the pattern of FOS rearrangements observed in benign bone and vascular tumours." (PMID 36426824, 2023).
viral infections (1 paper, 2017). "We hypothesized that FOSL1 may translocate from the nucleus to the cytoplasm after stimulation or viral infection, thus regulating the IFN-I pathway." (PMID 28049150, 2017). "As a negative regulator of the IFN-I response, FOSL1 may also affect the host response to viral infections." (PMID 28049150, 2017). "Our data suggest that FOSL1 interacts with TRAF3 and TRIF in immune cells after viral infection." (PMID 28049150, 2017).
tumor (229 papers, 2002 to 2026). "Integrative multi-omics analyses revealed that SMARCA4 directly cooperates with FOSL1 at active enhancers, leading to the activation of tumor-associated transcriptional programs." (PMID 42010258, 2026). "Integrated analysis of RNA sequencing and NSUN2 RIP-seq identified several candidate target genes (including STC1, CDCP1, FOSL1, and Serpine1) associated with tumor invasion and neuronal interactions 22-25." (PMID 41356184, 2026). "Note repressed expression of RASGRF1 and DMBT1 was associated with increased tumor size, and high expression of FOSL1, FAM83A and MYEOV was associated with poor survival." (PMID 38245882, 2024). "miR-19a-3p has also been implicated in the regulation of FOSL1 in tumor-associated macrophages (TAMs)." (PMID 38791400, 2024). "In line with the in vitro data, HNSCC cells with FOSL1 loss showed decreased rates of subcutaneous tumor growth and pulmonary metastasis." (PMID 38791400, 2024). "Most likely, the existence of a NF1-MAPK-FOSL1 axis goes beyond GBM pathogenesis since FOSL1 appears to be upregulated in concomitance with NF1 mutations in multiple tumor types." (PMID 34399888, 2021). "Further analysis of patient-derived xenografts revealed upregulation of FOSL1 expression in tumours with KRAS mutations compared to wild type." (PMID 28220783, 2017). "Although FOSL1 inhibition involved the regulation of mitotic genes, sensitivity of mutant KRAS cells to FOSL1 loss seems to occur irrespectively of the proliferative rate of tumour cells." (PMID 28220783, 2017). "We also found that high levels of FRA1 gene (FOSL1) expression independently predicted poor recurrence-free survival and was associated with a higher T-stage, an index of advanced tumor invasion." (PMID 24658684, 2014). "FOSL1 is responsible for inducing changes in the structure and arrangement of the cytoskeleton, loss of polarization in epithelial cells, increased ability to move, and invasion of tumor cells." (PMID 38791400, 2024). "First, both tumor cells and tumor-associated immune cells often express FOSL1." (PMID 35163444, 2022). "And low expression of FOSL1 in the cytoplasm was linked with advanced tumor stage." (PMID 32587640, 2020). "All in all, these observations indicate that FOSL1 links KRAS oncogene to genes involved in mitotic fitness, and suggest that AURKA and TACC3 may partially mediate the ‘synthetic sensitivity' of mutant KRAS tumours to FOSL1 loss." (PMID 28220783, 2017). "In addition, a higher expression of FOSL1 occurs in tumor-associated macrophages." (PMID 35163444, 2022). "Moreover, higher FOSL1 levels are observed in tumor-associated macrophages." (PMID 35163444, 2022). "This positions FOSL1 as an upstream regulator of IL‐6 signaling, which contributes to the persistence of therapy‐resistant tumor populations." (PMID 41556041, 2026). "Immunohistochemical analysis revealed that FOSL1 staining intensity was markedly elevated in tumor cells from TMZ‐resistant GBM patients relative to those from TMZ‐sensitive patients." (PMID 41556041, 2026). "The reduction in Fosl1 expression suggests a possible inhibition of tumor growth and invasive potential." (PMID 41282050, 2025). "The MRI results indicated that the LN229R group with FOSL1 knockdown exhibited notably slower tumor growth compared to the LN229R control group." (PMID 41423530, 2025). "For example, FOSL1 can induced the formation of superenhancers (SEs) that bind to tumor-related genes (such as metastasis-promoting genes), thus promoting gene expression and cancer cell migration." (PMID 40821785, 2025). "This included the downregulation of FOS-like antigen 1 (FOSL1), which has been associated with the potent anti-tumor effects of panobinostat in UPS." (PMID 41319167, 2025). "FOSL1 can also promote the reprogramming of cancer cells with other phenotypes of CSCs, thus promoting tumor metastasis." (PMID 40821785, 2025).
tumor (continued). "In ovarian cancer, miR-134 can form a positive feedback loop with FOSL1, which reduces the sensitivity of tumor cells to chemotherapy drugs." (PMID 40821785, 2025). "In contrast, the LN229R group with concurrent FOSL1 knockdown and PRMT1 overexpression demonstrated accelerated tumor progression in comparison to the group featuring FOSL1 knockdown, PRMT1 overexpression, and CAPS knockdown." (PMID 41423530, 2025). "FOSL1 affects the progression of cancer mainly through the transcription of a series of tumor-related genes by binding the promoters, introns and distal enhancers in the binding regulatory sequence." (PMID 40821785, 2025). "FOSL1 not only affects the occurrence and development of tumors but also affects the drug resistance of tumor cells, and it is beneficial to the survival of drug-addicted cancer cells when the drug is withdrawn." (PMID 40821785, 2025). "In macrophages, the M2 phenotype can promote tumor development, while FOSL1 can prevent macrophages from differentiating into the M2 phenotype by activating the STAT3 pathway and other downstream pathways." (PMID 40821785, 2025). "Its target gene, FOSL1, a transcription factor involved in tumor progression, was found to be overexpressed in TNBC cells, suggesting a tumor-suppressive role for miR-4516." (PMID 40867639, 2025). "The AP-1 transcription factor FOSL1, also known as Fra-1, is a crucial oncoprotein that plays an important role in human tumor progression and metastasis and has thus emerged as a promising therapeutic target." (PMID 40821785, 2025). "This aligns with prior research on KRAS-induced FOSL1 and NF-κB signaling in tumor dedifferentiation and metastasis." (PMID 40634284, 2025). "In tumor cells, CircCRIM1 can bind to miR-34c-5p to prevent its function and then indirectly promote the expression of FOSL1." (PMID 40821785, 2025). "The limited understanding of the structure and function of FOSL1 hinders the development of strategies to target FOSL1 with small molecule inhibitors for tumor treatment." (PMID 38791400, 2024). "The knockdown of AGAP2-AS1 leads to the promotion of miR-195-5p expression, which, in turn, inhibits FOSL1 ectopic expression, subsequently impeding tumor progression." (PMID 38791400, 2024). "FOSL1 can transform mature cancer cells into stem-like cells that can propagate the tumor by controlling transcription factors related to stemness." (PMID 38791400, 2024). "The findings indicated that there is a strong correlation between high FOSL1 ectopic expression and larger tumor size, advanced T stage, and lower survival rates." (PMID 38791400, 2024). "The expression of genes measured at the end of treatment confirmed that improved tumor control is linked to a stronger inhibition of genes that report on the activity of MAPK signaling (e.g., FOSL1, DUSP6, and SPRY4)." (PMID 39199684, 2024). "FOSL1, a transcription factor from the activator protein-1 (AP-1) superfamily, plays a significant role in various cancers by promoting tumor growth, survival, differentiation, and invasion." (PMID 38791400, 2024). "We observed coexpression of LTR10 and FOSL1 in tumor-specific epithelial cells for 10 of these patients, consistent with a role for AP1 signaling in regulating LTR10 elements." (PMID 39018396, 2024). "Strong and diffuse overexpression of the nuclear transcription factor FOSL1 has been recently identified in 80% to 100% of soft tissue desmoplastic fibroblastoma, which is regarded as a specific feature of this tumor type." (PMID 39830562, 2024). "Our findings revealed that POSTN secreted from GSCs promotes GSC self-renewal and tumor growth via activation of the αVβ3/PI3K/AKT/β-catenin/FOSL1 pathway." (PMID 39227950, 2024). "POSTN secreted from GSCs promotes GSC self-renewal and tumor growth via activation of the PI3K/AKT/β-catenin/FOSL1 pathway." (PMID 39227950, 2024).
tumor (continued). "In this study, we showed that POSTN secreted from GSCs promotes GSC self-renewal and tumor growth via activation of the αVβ3/PI3K/AKT/β-catenin/FOSL1 pathway." (PMID 39227950, 2024). "FOSL1 depletion disrupts SEs and inhibits the expression of these critical oncogenes, leading to tumor initiation and metastasis suppression." (PMID 38791400, 2024). "They indicated that the recurrence of the tumor is delayed when the expression of FOSL1 is increased." (PMID 38791400, 2024). "The oncoprotein FOSL1’s overexpression is correlated with tumor progression and worsened patient survival." (PMID 38856747, 2024). "HE staining and immunohistochemical analysis revealed that POSTN knockdown reduced tumor growth and the expression of β-catenin and FOSL1, the GSC marker CD133, and the proliferation marker Ki67." (PMID 39227950, 2024). "Deletion of FOSL1 prompts a change from a mesenchymal to a proneural transcriptional signature, and results in a reduction in both stemness and tumor growth." (PMID 38791400, 2024). "Mechanistically, A3A in tumor cells is the main mutator contributing to APOBEC mutagenesis in ESCC, and its overexpression is regulated by transcription factor (TF) FOS Like 1 (FOSL1)." (PMID 37215984, 2023). "In a rat kidney cell system, in which the tyrosine kinase receptor TrkB triggered in vitro motility and invasiveness along with lung metastasis of tumor xenografts, Fosl1 was identified among the top overexpressed genes." (PMID 37176013, 2023). "Enriched PRSS3, PAR2, and FOSL1 in human tumor samples and their correlations with worse outcomes reveal their clinical significance." (PMID 37395651, 2023). "Fra-1, also known as FOSL1, is highly expressed in most solid tumors and is closely related to the proliferation and apoptosis of tumor cells." (PMID 36831172, 2023). "For example, FOSL1 is expressed in tumour tissue where it promotes growth and differentiation rather than apoptosis." (PMID 36517693, 2023). "The seminal findings on the Fosl1 requirement for placental vascularization, along with the FOSL1 role in endothelial cell migration and assembly of capillaries, suggested the Fra-1 involvement in tumor angiogenesis." (PMID 37176013, 2023). "Across both tumour types, concordance between FOSL1 immunohistochemistry and targeted sequencing results was 90%." (PMID 36426824, 2023). "It is thus highly plausible that FOSL1 rearrangements operate through the same mechanism, i.e. reduced FOSL1 protein degradation, which is supported by our finding of intense FOSL1 protein immunoreactivity in mutant tumours." (PMID 36426824, 2023). "Consistently, one of the AP1 factors, FOSL1, has highly enriched binding sites in tumor-specific hypoDMRs as well as upregulated mRNA expression in EAC tumors relative to NGEJ." (PMID 37620896, 2023). "Although the 5FU-induced EMT regulation in colorectal PDS was not significantly linked to disease recurrence, one gene marker within this category (FOSL1) correlated both with tumor relapse and DSF in patients." (PMID 35562738, 2022). "The results of immunohistochemistry analysis demonstrate a positive correlation of FOSL1 level with the tumor grade." (PMID 35163444, 2022). "FOSL1 expression correlates with the depth of the tumor, the presence of metastases in the lymph nodes, stage, and aggressive behavior." (PMID 35163444, 2022). "Despite intense staining for FOSL1 in tumor cells, the healthy epithelia either remain FOSL1-negative or express FOSL1 at low levels." (PMID 35163444, 2022). "Second, FOSL1 expression is higher in EMT-transformed tumor cells that can potentially enter the bloodstream and invade healthy tissues." (PMID 35163444, 2022). "In solid tumors, FOSL1 controls the progression of tumor cells through the epithelial–mesenchymal transformation." (PMID 35163444, 2022). "Higher FOSL1 expression is associated with EMT, which precedes tumor dissemination, and plays a crucial role in the survival of the cancer cells." (PMID 35163444, 2022).